VDR (vitamin D receptor)
Diseases named in the same sentence as VDR in open-access papers (continued):
Sharing a sentence is not in itself a finding about the gene and the disease.
preeclampsia (continued). "In contrast to VDR and miR-26b-5p expression, COX-2 expression was obviously increased in the placentas from preeclamptic pregnant women, suggesting that upregulation of placental COX-2 expression is associated with downregulation of VDR and miR-26b-5p expression in women with preeclampsia." (PMID 34045549, 2021). "The finding of anti-inflammatory property by vitamin D through promotion of VDR/miR-26b-5p expression provides significant evidence that downregulation of vitamin D/VDR signaling could contribute to increased inflammatory response in preeclampsia." (PMID 34045549, 2021). "In the current study, we demonstrate that placental LAT1 expression is reduced in women with preeclampsia, and 1,25(OH)2D3 stimulates LAT1 expression through VDR in cultured placental trophoblasts." (PMID 35301401, 2022). "We assessed the expression of CYP27B1, an activator of calcidiol, and Vitamin D receptor (VDR) in placentae from NW and OB, and women with gestational diabetes and preeclampsia." (PMID 35712242, 2022). "We next examined VDR expression in placentae from pregnancies complicated by gestational diabetes regulated by insulin (A2GDM) and preeclampsia (PE)." (PMID 35712242, 2022). "The analysis of the final models points toward a relevance of AR, VDR, SLC6A2, NOS3 and CHRM4 as targets for preeclampsia." (PMID 33546161, 2021). "1,25(OH)2D3 was used as bioactive vitamin D. Our results showed that reduced VDR and miR-26b-5p expression, but increased COX-2 expression, was observed in the placentas from women with preeclampsia compared to those from normotensive pregnant women." (PMID 34045549, 2021). "Single‐nucleotide polymorphisms (SNPs) were genotyped 50 kilobases up‐ and down‐stream in three genes (VDR,GC, and CYP27B1) in the samples from both studies, for a total of 744 preeclampsia cases and 2411 controls." (PMID 29380949, 2018). "Given its importance and relevance in gestational outcome, Vitamin D Receptor (VDR) SNPs have been studied in PE and gestational hypertension." (PMID 30618791, 2018). "Serum and placental samples from four groups of cases; normal term, IUGR, early-onset and late-onset preeclampsia, were analyzed for 25(OH)D vitamin D, sFLT1, PGF, LGALS13 in serum and vitamin D receptor (VDR), MAP1LC3B and BECN1 in placental tissues." (PMID 30408071, 2018). "In preeclampsia, which has significant pathophysiological overlaps with FGR, VDR expression is decreased." (PMID 29113124, 2017). "No changes in VDR expression relative to BMI-matched controls were observed in the placentae of women with gestational diabetes or preeclampsia." (PMID 35712242, 2022). "mRNA expression of placental CYP24A1, CYP27B1 and VDR (mean ± SD and (range) do not differ between patients with preeclampsia and healthy controls." (PMID 25148115, 2014). "Placental gene expression of neither CYP24A1 nor CYP27B1 nor VDR differed between seasons or between patients with preeclampsia and healthy controls (as determined by the Mann-Whitney test)." (PMID 25148115, 2014). "Silencing of the VDR also impaired tubule formation (percent relative to control sera alone: 59±7.2%; P = 0.01; n = 4; percent relative to preeclampsia sera alone: 78±2.6%; P = 0.01; n = 4), (data compared to non-silenced control ECFCs)." (PMID 24887145, 2014). "The effects of VDR and VEGF inhibitors (P5P and SU4516, respectively) on ECFC tubule formation were tested in the presence of pooled control sera or pooled preeclampsia sera." (PMID 24887145, 2014). "Vitamin D significantly increased tubule formation in the presence of uncomplicated pregnancy or preeclampsia sera (control = sera without VDR or VEGF inhibitors)." (PMID 24887145, 2014). "Patients with preeclampsia displayed lower vitamin D serum levels in response to seasonal changes.The regulation of placental CYP24A1, but not of the VDR or CYP27B1 might be altered in preeclampsia." (PMID 25148115, 2014).
atherosclerosis (33 papers, 2012 to 2025). A disease characterized by the build-up of fatty material and calcium deposition in the arterial wall resulting in partial or complete occlusion of the arterial lumen. "Growing evidence has shown that vitamin D has an extensive noncalcemic pleiotropic function mediated by vitamin D receptor (VDR), associated with suppression of the renin-angiotensin system, anti-myocyte hypertrophy, atherosclerosis lowering and anti-inflammation." (PMID 35311238, 2022). "Although total loss of VDR promotes leanness, activation of VDR signaling in the immune system may improve insulin resistance and cardiovascular aspects of MetS, including atherosclerosis." (PMID 30828578, 2018). "Additionally, vitamin D/VDR signaling is important for protecting against atherosclerosis, the pathology ultimately underlying death in HGPS patients." (PMID 27145372, 2016). "Furthermore, VDR has a wide spectrum of effects on various cells types implicated in atherosclerosis, including ECs, VSMCs, and immune cells." (PMID 26322890, 2015). "Taq-I and Bsm-I vitamin D receptor gene polymorphisms are associated with the atherogenic serum lipid profile and metabolic disorders, which may increase the risk of atherosclerosis and cardiovascular disease in an ethnically homogenous postmenopausal population of women from Poland." (PMID 37375641, 2023). "It is thought that vitamin D binding sites may be altered by some VDR gene polymorphisms including TaqI polymorphism, which affects the function of VDR and may lead to inflammatory responses participating in an increased risk of developing atherosclerosis and CAD." (PMID 36882686, 2023). "A number of studies reported that VDR expression can be altered under pathological conditions such as atherosclerosis, where inflammation and oxidative stress also negatively impact on vitamin D signalling." (PMID 40261445, 2025). "Vitamin D is involved in cardiovascular protection, but only few studies examined the impact of the VDR in atherosclerosis." (PMID 29401665, 2018). "It has been found that macrophage VDR signaling attenuates atherosclerosis in mice in part by inhibiting the local renin-angiotensin system." (PMID 30319417, 2018). "The results reveal an important role for basal levels of endothelial VDR in limiting endothelial cell inflammation and atherosclerosis." (PMID 26322890, 2015). "Even though further studies should address the role of VDR in lipid metabolism, our current results suggest that the more severe atherosclerosis in apoE-/-VDR-/- mice occurred despite improved serum lipid profiles." (PMID 26322890, 2015). "Our aim was to assess the role of basal levels of vitamin D receptor (VDR) on the early leukocyte recruitment and related endothelial cell-adhesion-molecule expression, as essential prerequisites for the onset of atherosclerosis." (PMID 26322890, 2015). "To study the effects of VDR deletion on atherosclerotic plaque development in vivo, we combined a genetic model of VDR deletion with a mouse model of experimental atherosclerosis, the apolipoprotein E knockout (apoE-/-) mouse." (PMID 26322890, 2015). "Data reported here provide novel information on the role of VDR signaling in endothelial cell homeostasis and in atherosclerosis." (PMID 26322890, 2015). "Vitamin D receptor is expressed in cardiomyocytes and vascular endothelial cells, which may be related to the regulation of vascular tension and atherosclerosis." (PMID 35669075, 2022). "Furthermore, VDR inhibits the initiation of endothelial inflammatory diseases, like atherosclerosis, and reducing inflammatory cytokine/chemokine production in macrophages, when it is activated by vitamin D." (PMID 31354906, 2019). "Previous studies have shown the role of vitamin D and the VDR in the process of atherosclerosis." (PMID 26322890, 2015). "Furthermore, we examined the effects of VDR deletion on atherosclerotic lesion formation in the apoE-/- atherosclerosis model." (PMID 26322890, 2015).
atherosclerosis (continued). "As with the conflicting atherosclerosis data, this may reflect differences in the degree of attenuation of VDR signalling." (PMID 24586387, 2014). "Other groups have explored whether VDR plays a beneficial role in atherosclerosis." (PMID 34360540, 2021). "However, a causal relationship between reduced VDR expression and leukocyte-endothelial cell interplay leading to atherosclerosis has not yet been established." (PMID 26322890, 2015). "Interestingly, accelerated lesion formation in apoE-/-VDR-/- mice was not correlated with serum lipid levels, known to be the major risk factor for atherosclerosis." (PMID 26322890, 2015). "Interestingly, following the discovery that FOXP3 transcription is directly targeted by VDR, also some beneficial effects of vitamin D might involve the regulatory T-cell (Treg) subtype that has been described to reduce atherosclerosis." (PMID 24459602, 2013). "In summary, gut microbiota-derived secondary BAs play important roles in the development of atherosclerosis through the modulation of various BA receptors such as FXR, PXR, TGR5, VDR, and S1PR2." (PMID 30319417, 2018). "Another study showed that macrophage VDR signalling, in part by suppressing the local RAS, inhibits atherosclerosis in mice." (PMID 29401665, 2018). "In vascular tissues, one of the top KDs for the shared CAD/atherosclerosis pathways between species is ZHX2, whose subnetwork neighbors are highly enriched for genes in a co-expression module annotated with RXR/VDR pathway, post translational protein modification, and endocytosis terms." (PMID 38060277, 2023). "Genes downregulated in pWAT T cells RNA seq, were part of inflammatory processes (complement system, antigen presentation), RXR activation (LXR/RXR activation, VDR/RXR activation), phagocytosis (FCγ receptor mediated phagocytosis), and atherosclerosis signaling." (PMID 33772096, 2021). "To study the functional role of VDR in atherosclerosis, we generated animals lacking both VDR (VDR-/-) and apoE (apoE-/-) gene." (PMID 26322890, 2015). "Indeed, in the absence of atherosclerosis and macrophage accumulation, VDR ablation was still associated with an increased arterial expression of adhesion molecules implying that the enhanced plaque formation in apoE-/-VDR-/- mice was due to a strong proinflammatory milieu fostered by VDR deletion." (PMID 26322890, 2015). "Data from our VDR−/− mouse study show that vascular mineralization was not simply the consequence of accelerated atherosclerosis because calcification occurred in vessel walls that were free of any atherosclerotic plaques." (PMID 22536373, 2012). "In addition, VDR knockout mice exhibit phenotypes observed in HGPS patients, such as premature aging, atherosclerosis, and cardiovascular disease (CVD), suggesting that impaired VDR activity could contribute to the pathophysiology of HGPS." (PMID 27145372, 2016).
Parkinson disease (32 papers, 2015 to 2026). A progressive degenerative disorder of the central nervous system characterized by loss of dopamine producing neurons in the substantia nigra and the presence of Lewy bodies in the substantia nigra and locus coeruleus. "Abnormalities in the vitamin D receptor, and low levels of vitamin D were both linked to Parkinson's disease and autism." (PMID 35002805, 2021). "VDR polymorphisms influence susceptibility for cognitive decline in average, 67.4 years old patients with Parkinson’s disease." (PMID 32554862, 2020). "Particularly, the functional VDR polymorphism Fokl, is associated with cognitive decline in patients with Parkinson’s disease, which worsen with each additional copy of the allele." (PMID 32554862, 2020). "Multiple meta-analyses have examined the association between VDR polymorphisms and risk of Parkinson's disease." (PMID 32536905, 2020). "Another functional polymorphism of VDR, namely, Fokl, was found to be associated with cognitive decline in American patients with Parkinson’s disease." (PMID 28426778, 2017). "The VDR pathway has also been implicated in P-gp downregulation in Parkinson’s disease." (PMID 36498995, 2022). "Associations between VDR genotypes and the risk for Parkinson’s disease." (PMID 35517045, 2022). "Moreover, it has also been observed alterations in neuronal differentiation not only in VDR deficient mice but also in a mice model of Parkinson’s disease in which MPTP downregulates VDR expression." (PMID 32554862, 2020). "Preliminary data suggest that single nucleotide polymorphisms (SNPs) in the VDR gene may have roles in the development of multiple sclerosis, Parkinson’s disease, and Alzheimer’s disease." (PMID 29160835, 2017). "Differently, VDR was downregulated in a mouse experimental model of Niemann–Pick Type A Disease and Parkinson’s disease." (PMID 39062692, 2024). "The evidence involving vitamin D receptor (VDR) polymorphisms and Parkinson's disease risk and severity, however, has been inconsistent." (PMID 32536905, 2020). "We have recently found a down-regulation of nSMase and a decrease of glial fibrillary acidic protein (GFAP) and vitamin D receptor (VDR) in the gyrus dentatus (GD) of hippocampus from neurodegenerative mouse model of Parkinson’s disease (PD)." (PMID 31086057, 2019). "In this scenario, we previously studied the nSMase and VDR changes in hippocampal GD of MPTP induced Parkinson’s disease." (PMID 31086057, 2019). "In a study of the Chinese population, VDR gene polymorphism and Parkinson’s disease were not correlated." (PMID 40464816, 2025). "Next, we discuss the results of preclinical and clinical studies evaluating the significance of vitamin D status and the efficacy of vitamin D supplementation in the treatment of Parkinson’s and Alzheimer’s diseases, emphasizing the possible role of the VDR in these phenomena." (PMID 36831327, 2023). "In two separate mice models of Parkinson’s disease (6-hydroxydopamine-induced model, and α-synuclein preformed fibril injection model), transcriptional repression of the VDR gene and its downstream target gene, MDR1a, were restored upon treatment with 1α,25-dihydroxyvitamin D3." (PMID 36498995, 2022). "Amantadine, an FDA-approved antiviral and anti-Parkinson agent, is associated with a monocyte-macrophage-like differentiation of HL60, U937, and Kasumi-1 myeloid leukemia cell lines by inducing vitamin D receptor (VDR) expression." (PMID 33776757, 2021). "A comprehensive literature review was conducted to evaluate the mechanisms underlying Vitamin D3's neuroprotection and Vitamin A's modulatory role through RXR activation, focusing on studies exploring the VDR-RXR heterodimer in Alzheimer's and Parkinson's disease models." (PMID 42037680, 2026).
Parkinson disease (continued). "In a randomized double blind control trial of patients with Parkinson disease (PD), the effect of vitamin D3 (1200 IU/day for 12 months) to stabilize PD were only associated with the VDR FokI TT or CT but not the other SNPs examined (i.e., BsmI, Cdx2, ApaI and TaqI)." (PMID 31167402, 2019).
diabetic nephropathy (30 papers, 2012 to 2026). "Future research should expand the genetic analysis of diabetic nephropathy by including additional vitamin D receptor polymorphisms, such as BsmI, ApaI, and FokI, alongside the TaqI polymorphism." (PMID 40575263, 2025). "The multifaceted capabilities of parthenolide, from its influence on diabetic nephropathy-associated complications to its modulation of VDR expression, position it as a potential therapeutic agent in managing diabetic nephropathy." (PMID 38318147, 2024). "Multiple stepwise regression analysis and correlation analysis demonstrated that a reduction of PTPN2 is associated with lower VDR and higher uACR, a major indicator for assessing the development of diabetic kidney disease." (PMID 30246029, 2018). "Inflammation and oxidative stress are associated with pathogenesis of diabetic nephropathy (DN) and found to be regulated by nuclear receptors such as vitamin D receptors (VDR)." (PMID 26180775, 2015). "Furthermore, FokI polymorphisms in the vitamin D receptor (VDR) gene differ between patients with diabetic nephropathy and healthy subjects." (PMID 23226566, 2012). "Main findings from clinical studies of vitamin D and vitamin D receptor activators treatment in diabetic nephropathy patients." (PMID 40134933, 2025). "VDR agonists can also effectively ameliorate the progression of diabetic nephropathy by reducing renal inflammation." (PMID 40804707, 2025). "Such downregulation of the VDR has also been observed in other diabetic complications, such as diabetic kidney disease (DKD), potentially attributable to multiple factors, including hyperglycemia, inflammation, and oxidative stress." (PMID 40565182, 2025). "For example, studies on rats with diabetic nephropathy demonstrated the local renal anti‐inflammatory effect of vitamin D receptor activation." (PMID 40804707, 2025). "DDIT4 is an important target of VDR/mTOR/p70s6k/4E-BP1 signaling pathway induced by high glucose in diabetic nephropathy." (PMID 38567351, 2024). "Tan was superior to Par in ameliorating tubulointerstitial fibrosis by regulating VDR/Wnt/β-catenin pathway in rats with diabetic nephropathy." (PMID 37991543, 2024). "A recent study found that AMPK plays a central role in the amelioration of kidney injury in diabetes nephropathy (DN) by the vitamin D (VD)-vitamin D receptor (VDR)." (PMID 37635982, 2023). "Deb and his group provide evidence that podocyte VDR signaling protects podocytes from hyperglycemia-induced apoptosis and prevents diabetic nephropathy." (PMID 33294462, 2020). "In our study, we provided an evidence that the VDR signaling in podocytes has potent renoprotective activities against diabetic nephropathy, and the podocyte VDR at least in part mediates the antifibrotic action of 1,25(OH)2D3 and its analogs." (PMID 33294462, 2020). "Studies have confirmed that VDR polymorphisms affect CKD occurrence and progression such as diabetic nephropathy, lupus nephritis, and hypertensive renal damage." (PMID 31218132, 2019). "We investigated the expression of PTPN2 in T2DM and its correlation with the severity of diabetic kidney disease, VDR, and inflammatory factors MCP-1, IL-6, and TNFα." (PMID 30246029, 2018). "The following genes had significant association with diabetic nephropathy: eNOS, AT2R, SUMO4, IL-10, VEGF, MTHFR, ACE, and VDR." (PMID 26587547, 2015). "More recent studies suggests that the effect of vitamin D receptor activation is partly that of negatively regulating renin-angiotensin system, which plays a significant role in the development of diabetic kidney disease." (PMID 28197449, 2014). "The VDR/Atg3 axis regulates autophagy and inhibits the development of diabetic nephropathy." (PMID 41141390, 2026). "Therapeutic implications of vitamin D and vitamin D receptor activators in diabetic nephropathy." (PMID 40134933, 2025).